SRC (SRC proto-oncogene, non-receptor tyrosine kinase)
Diseases named in the same sentence as SRC in open-access papers (continued):
Sharing a sentence is not in itself a finding about the gene and the disease.
cancer (continued). "ITGBL1 is known to promote cancer metastasis and invasion by the WNT/PCP, FAK/SRC, and TGF-β signaling pathways, yet our previous study suggested that ITGBL1 was a secreted protein and that it inhibited integrin activation." (PMID 35066808, 2022). "On the other hand, SRC, CASP3, EGFR, ERBB2, mTOR, MMP9, and HIF1A followed the proteoglycans in cancer." (PMID 35959427, 2022). "Based on NCBI BioSystems pathway analysis, the results showed that MAPK14, SRC and MAPK1 belonged to senescence and autophagy in cancer." (PMID 36271672, 2022). "AKT1, EGFR, SRC, ESR1, and PTGS2 are the top five targets in the PPI network, and they were reported as critical regulatory factors in cancer metastasis and EMT." (PMID 35942366, 2022). "Most of the drugs highly similar to BR were enriched with anti-cancer drugs, and their known MoAs included the inhibition of epidermal growth factor receptor, RAF, MAPK/ERK Kinase, SRC, and mTOR signaling pathways." (PMID 36304143, 2022). "Further analysis using bioinformatics prediction was performed to show that ERBB2, SRC, TNF receptor, and AKT1 are potential key targets and play an essential role in cancer treatment." (PMID 36500678, 2022). "On the other hand, SRC, CASP3, EGFR, ERBB2, mTOR, MMP9, and HIF1A followed the proteoglycans in cancer (degree 7)." (PMID 35959427, 2022). "The seed genes in the functional modules, SRC and VDR were found to be upregulated in cancer tissue samples compared to normal breast samples." (PMID 35273218, 2022). "Among the common kinases, the mTOR, AKT1, SRC, FYN, and GNB2L1 are the kinases that are common in ALS and cancers and also identified as hub genes from the PPI network." (PMID 36590916, 2022). "Phosphorylation of STAT3 at Y705 by SRC and JAK leads to transcription of genes involved in cancer progression, including those regulating apoptosis." (PMID 35732128, 2022). "It has been reported that most of the 8 ARGs (VIM, UFM1, TSC2, SRC, MEFV, CTTN, CFTR and CDKN1A) are related to cancer." (PMID 35121801, 2022). "While SRC mRNA expression is more widely distributed, distinct subsets of cells coexpress both PTK6 and SRC in both cancers." (PMID 36228719, 2022). "On the one hand, phosphorylation of STAT3 at Tyr705 by tyrosine kinases such as JAK and SRC or at Ser727 by JNK and other MAPKs results in its activation in cancer." (PMID 35145111, 2022). "In all the carcinoma and hematopoietic cancer networks, STAT1 and STAT3 interact with a similar panel of proteins, including MTOR, SRC and EGFR." (PMID 35229974, 2022). "Schoenherr and colleagues have recently shown that AMBRA1 is involved in SRC/FAK1-dependent polarization and chemotactic invasion of cancer cells through its interaction with FAK1 and several trafficking proteins, thus regulating adhesion and migration." (PMID 33953176, 2021). "Additionally, the SRC protein, in a phosphorylation-dependent manner, interacts with a large number of regulatory pathways in the cell cycle and signal transduction, which influence the carcinogenesis processes in relation to development and cancer progression." (PMID 34207568, 2021). "Taken together, we unveiled Src42A/SRC is a critical transcriptional target for Yki/YAP-induced tumor cell migration, and provided SRC as a potential therapeutic target for Hippo-related cancers." (PMID 34862372, 2021). "Several ANO1-related signaling pathways, including EGFR-mediated AKT/SRC/ERK1/2 and Ras-Raf-MEK-ERK1/2, have been reported in cancer development." (PMID 34281152, 2021). "In cancer cells, signaling through S1PR1 leads to the activation of RAC1, SRC, PTK2/FAK1, as well as MAP kinases, and influences cell proliferation and survival in GBM." (PMID 34359681, 2021).
cancer (continued). "Only in cancer affected tissue, ESR1/SRC and ESR2/PELP1 ratios were both positively correlated with PELP1/SRC (moderately strong) and ESR2/SRC (strong), respectively." (PMID 34207568, 2021). "The SRC oncogene was followed by MYC, ERBB/EGFR, and RAS oncogenes whose identification in diverse human cancers consolidated the view of cancer as a genetic disease." (PMID 34070384, 2021). "These two targets have a few interacting proteins in common such as TIMP (1, 2 and 3), STAT 3, VEGF A, SRC, DCN, MMP 10 and CD 44 and all are supposed to be plum targets for cancer therapies." (PMID 34075089, 2021). "In the case of ESR1, in tissue obtained from cancer patients, there was a significant correlation with PELP1 and SRC expression." (PMID 34207568, 2021). "A recent study has found that the SRC gene is one of the targeting sites of GPX4, the differential expression of which regulates cell proliferation, cancer progression, apoptosis, and ferroptosis." (PMID 34568341, 2021). "Since both, dasatinib and ponatinib also target ABL kinase, and dasatinib, WH-4-023, Ponatinib target the SRC kinase, our finding reveals that the high-ELF4 cancers are likely to signal through SRC and ABL kinases." (PMID 33836003, 2021). "In FGFR-overexpressing cancer cells, tyrosine phosphorylation of STAT3 is also dependent on the concomitant FGFR-dependent activity of SRC and JAK2 kinase." (PMID 34439322, 2021). "In human cancers, the level of p27KIP1 is frequently interfered by MAPK, SRC, and receptor tyrosine kinase tracks." (PMID 34853592, 2021). "Taken together, our results show for the first time amoeboid motility related to SRC‐mediated activation of the Rho/ROCK/pMLCII pathway via the RASSF1C oncogene, in cancer cells where the tumor suppressor RASSF1A is epigenetically silenced (schematic model)." (PMID 34532864, 2021). "Oncoviruses can lead to the onset and progression of cancer via commonly shared pathways including WNT/β-catenin, JAK/STAT/SRC, PI3k/Akt/mTOR, and/or RAS/MEK/ERK signaling pathways." (PMID 32521661, 2020). "This was also true for SRC and LYN, although less patient samples were tested due to limited availability of cancer tissue." (PMID 32082487, 2020). "It has been reported that, when activated, SRC promotes tumorigenesis through its downstream signaling pathways, including PI3 kinase/Akt/mTOR and MEK/ERK, to facilitate cancer growth, migration, invasion, and metastasis, as well as chemotherapy resistance." (PMID 32435511, 2020). "A recent study demonstrated PTPN13 involvement in cisplatin sensitivity of HNSCC cell lines (WSU-HN6 and CAL-27) where cancer-derived IgG inhibition upregulates PTPN13, resulting in the inhibition of the SRC/PKD1/AKT pathway." (PMID 33322542, 2020). "This is consistent with the well-established ability of SRC to interact and activate the prosurvival factor AKT, which plays an important part in several human cancers, including MM." (PMID 32664483, 2020). "Later on, the interplay between SRC and MYC has been described in several other cancers, such as melanoma, non-Hodgkin lymphoma, osteosarcoma, and lung cancer." (PMID 32545574, 2020). "In accordance with previous data from our laboratory concerning syntenin‐dependent cargo (SRC, FGF, Frizzled 7), this result reinforces the notion of the syntenin‐SDC exosomal pathway as an important player in cancer progression." (PMID 33343836, 2020). "We next evaluated by immunohistochemistry the expression of various SRC effectors, such as CTTN, FAK, and ASAP1, known to regulate tumor invasion, metastasis, and aggressive phenotypes in HNSCC and other cancers." (PMID 31731442, 2019).
cancer (continued). "In human HCC patients, 75% of HCC cancer tissue were HBx positive, and 65.38% of HCC tissue were SRC positive in the Chinese population." (PMID 31795276, 2019). "Indeed, SRC pathway activation has been positively correlated with sensitivity to treatment with dasatinib and saracatinib in different cancer types, suggesting that SRC activation could potentially serve as a biomarker to guide SRC targeting and clinical efficacy." (PMID 31731442, 2019). "However, in cancer cells, aberrant HGF/c-Met axis activation, which is closely related to c-Met gene mutations, overexpression, and amplification, promotes tumor development and progression by stimulating the PI3K/AKT, Ras/MAPK, JAK/STAT, SRC, Wnt/β-catenin, and other signaling pathways." (PMID 29455668, 2018). "In particular, SRC together with YES, FYN and LYN were often found co-overexpressed in our cancer cell lines and tissue sections." (PMID 29937990, 2018). "The efficacy of combining SRC and MEK inhibitors has been previously investigated in various cancer cell lines." (PMID 29435137, 2018). "As indicated by our results, the mRNA expression levels of SRC, CDC42, WASL, and RHO were all changed during cancer cell migration." (PMID 28640862, 2017). "Gene Sets Enrichment Analysis showed that GGT promotes cancer progression through EMT, KRAS, SRC and PKCA pathways." (PMID 28404903, 2017). "Lastly, our method not only identified the known cancer genes but also detected the potential rare drivers (PTPN6 in THCA, SRC, GRB2 and PTPN6 in KIRC, MAPK1 and SMAD2 in HNSC)." (PMID 28938536, 2017). "Next, we questioned how TM4SF4 activates the JAK2/STAT3 pathway or SRC/FAK/STAT3 pathway, which also reinforces EMT or CSC-like properties of cancer cells." (PMID 29254164, 2017). "The genes that were shared by three different cancers (i.e., FGFR3, EPAS1, SRC, and FOXD3) are shown in coral, and the genes that were shared by two types of cancers (i.e., PPARG, FOXO1, CDK4, NKX3-1, PIK3R1, PRKCB and EDNRB) are shown in light pink." (PMID 28178311, 2017). "HuR is phosphorylated at tyrosine residues in tumor cells and has several consensuses for phosphorylation by Abl-1, SRC, Lyn, FAK, and EGFR tyrosine kinases, involved in aberrant regulation of centrosomes in cancer cells." (PMID 25803745, 2015). "To further examine the underpinnings of these observations, we investigated the relationships among SRC, TGFB1 and PPARB/D expression levels in human carcinomas from various organs." (PMID 24203162, 2014). "In this study, we demonstrated that the up-regulation of SRC is common in HCC and in other human cancers." (PMID 24130815, 2013). "An inhibitory interaction from aHDAC (activity of HDAC) to SRCpY527, a critical phosphorylation site for the auto-inhibition of SRC, is consistent with the direct and indirect interactions of HDAC isoforms with Src observed in multiple cancer contexts." (PMID 24367245, 2013). "Our results indicate that the overexpression of SRC (in both mRNA and protein level) plays a role in HCC formation and in the formation of various human cancers." (PMID 24130815, 2013). "It has been reported that the oncogenic activation of RTK, PI3K, SRC, or Ras-MAPK pathways cooperate to inactivate p27Kip1, accelerate its proteolysis or change its intracellular localization in human cancers through modifications in p27Kip1 phosphorylation." (PMID 22970236, 2012). "Phosphorylated SRC activates alternative receptors RTKs MET and FAK both of which promote mitogenesis and cancer cell growth." (PMID 22482061, 2012). "In this respect, it has recently been demonstrated that SRC-mediated transformation of MCF-10A cells involves the NF-κB-Lin28B-let7-IL-6 axis and this signaling axis generates cancer cells with stem cell like properties." (PMID 20691079, 2010).
cancer (continued). "Here, we conduct a comprehensive analysis of a mitophagy-related gene signature, composed of PRKN, PINK1, MAP1LC3A, SRC, BNIP3L, BECN1, and OPTN, across various cancer types, revealing significant differential expression patterns associated with molecular subtypes, stages, and patient outcomes." (PMID 39859167, 2025). "Targeting SRC with inhibitors such as dasatinib and NXP900 has demonstrated potent antitumor effects, and when combined with standard chemotherapy, these agents amplify cancer cell death and suppress tumor progression." (PMID 41300430, 2025). "The genes AKT Serine–Threonine Kinase 1 (AKT1) and SRC Proto-Oncogene, Non-Receptor Tyrosine Kinase (SRC), were up-regulated in the cancer compartment of PNI foci compared to non-PNI." (PMID 40075699, 2025). "CD36-mediated activation of SRC/MAPK, AKT/GSK3β/β-catenin signaling axes, STAT3, and SOX2 had been shown to induce epithelial-mesenchymal transition (EMT) and promote proliferation, cancer stemness, metastasis as well as drug resistance." (PMID 40709184, 2025). "Although some crucial pathways (e.g., MAPK, Apoptosis, ERBB, JAK-STAT) were not top-ranked, core genes within these pathways (AKT1, EGFR, CASP3, TNF, SRC) showed high connectivity in the PPI network, reinforcing their relevance to the anti-cancer mechanisms of Siegesbeckiae Herba constituents." (PMID 41006588, 2025). "Notably, PRKN exhibited the highest alteration frequency, affecting 34% of all cancer samples, followed by OPTN (21%), PINK1 (18%), SRC (15%), BECN1 (13%), MAP1LC3A (9%), and BNIP3L (5%)." (PMID 39859167, 2025). "Trans-cinnamate demonstrated strong binding affinities for SRC and ESR1 (-8.5 kcal/mol), suggesting that trans-cinnamate may promote cancer cell death through modulation of key signaling pathways involved in cell survival and apoptosis." (PMID 40877012, 2025). "Overall, these findings highlight the complex landscape of CNVs in PRKN, OPTN, PINK1, SRC, BECN1, BNIP3L, and MAP1LC3A across different cancer types, emphasizing the potential impact of these genetic alterations on cancer pathogenesis and the importance of considering CNVs in therapeutic strategies." (PMID 39859167, 2025). "STAT3 is activated by tyrosine kinases, such as JAK and SRC, but the mechanism by which STAT3 maintains its activated state in cancer cells remains unclear." (PMID 38760429, 2024). "These pathways may be inhibited (GSK-3β 16) or activated (Notch1 10, SRC 15) by ASPH in a cell type-specific manner, leading to heterogeneous responses to ASPH inhibition in different cancer cell lines." (PMID 38817852, 2024). "Similarly, SRC expression was significantly correlated with expression of the EMT markers SNAIL and TGFβ, and the cancer cell stemness marker ALDH1." (PMID 38097740, 2024). "PLXNB3 binds to and activates the MET receptor tyrosine kinase, leading to activation of the SRC non-receptor tyrosine kinase and subsequently focal adhesion kinase, which promotes cancer cell migration and invasion." (PMID 37768037, 2023). "In addition, epithelial-mesenchymal transition (EMT)-associated marker E-cadherin was repressed, while Vimentin was enhanced in SRC-GOF cells, revealing the potential roles for SRC kinase in cancer stemness and EMT regulations." (PMID 36633714, 2023). "Other critical nodes include AKT1, SRC, CTNNB1 and EGFR, which are related to cancer signalling." (PMID 36944690, 2023). "The non-receptor tyrosine kinase SRC is overexpressed and/or hyperactivated in various human cancers, and facilitates cancer progression by promoting invasion and metastasis." (PMID 37439249, 2023). "SRC has been reported to play a role in cancer progression, whereas for ARFRP1, no functional evidence has been presented yet." (PMID 37666855, 2023).
cancer (continued). "Recent studies have reported that integrin β like 1 protein (ITGBL1), which is also called the ten beta integrin EGF-like repeat domain, regulated various forms of cancer cell migration, invasion and metastasis through the WNT/PCP, FAK/SRC, and TGF-β signaling pathways." (PMID 35066808, 2022). "Therefore, for the first time, we propose a novel role for SRC as a common targetable node in MEKi resistance mechanisms of CRC, permitting effective cancer stem cell targeting." (PMID 35272617, 2022). "c‐SRC (hereafter SRC) is the well‐known prototype of a large family of nonreceptor tyrosine kinases that promotes cancer cell migration, invasion, proliferation and survival in different contexts." (PMID 34856074, 2022). "While a variety of data suggest SRC would be a good therapeutic target in cancer, SRC inhibitors were not effective when used alone." (PMID 36228719, 2022). "The nonreceptor tyrosine kinase SRC regulates many cellular signalling processes, and pharmacological inhibition has long been a target of cancer drug discovery projects." (PMID 34856074, 2022). "SRC and ERK1/2 regulate cancer cell migration, invasion and metastasis and, therefore, we tested whether combinations of MEK and SRC inhibitors could synergise to block invasion using a 3D organotypic collagen I invasion assay." (PMID 34856074, 2022). "Here, we evaluated the SRC/ABL kinase inhibitor, AZD0424, and its potential use as an anti‐cancer combination therapy by testing across a diverse range of in vitro and in vivo cancer models in parallel with quantitative pathway profiling at the post‐translational level." (PMID 34856074, 2022). "Numerous reports showed that non-receptor tyrosine kinase SRC is involved in oncogenic STAT3 activation across various human cancers." (PMID 36324587, 2022). "We show that AZD0424 potently inhibits the phosphorylation of tyrosine‐419 of SRC (IC50 ~ 100 nm) in many cancer cell lines; however, inhibition of cell viability, via a G1 cell cycle arrest, was observed only in a subset of cancer cell lines in the low (on target) micromolar range." (PMID 34856074, 2022). "To this end, we found that while SRC inhibitors promote cell death in cancer cells harboring oncogenic SRC, simultaneous inhibition of autophagy (by hydroxychloroquine or by ATG5 or ATG7 knockout) promotes apoptosis of cancer cells even further." (PMID 35647611, 2022). "As CCL2/CCR2 activated SRC and SRC interacts with MET to regulate receptor activation in carcinoma cells, we asked whether CCL2-mediated SRC activation was important for MET phosphorylation." (PMID 35405500, 2022). "Both SRC and PTGS2 were overexpressed in cancer tissues, and the corresponding inhibitors may be useful for ESCC treatment (p < 0.001)." (PMID 34764976, 2021). "Predominantly inactive in noncancerous cells, SRC is aberrantly activated in many cancer types, including breast, colon, prostate, pancreatic, and ovarian cancers." (PMID 34417202, 2021). "In cancer, macropinocytosis can be driven not only by oncogenes, such as RAS and SRC, but can also be stimulated by growth factors (e.g., EGF), and/or ruffling kinase (e.g., p21-activated kinase-1) to modulate cancer cell metabolism and nutrient internalization." (PMID 34112916, 2021). "As important cancer regulatory nodes, EGFR and SRC also cross-talk with the PI3K/AKT pathway." (PMID 34819120, 2021). "In addition, several mechanisms of cancer development are related to ANO1, such as the EGFR-mediated AKT/SRC/ERK1/2 or Ras-Raf-MEK-ERK1/2 pathways; nonetheless, the underlying mechanism is unclear in NSCLC." (PMID 34281152, 2021).